HNRNPCL1 (heterogeneous nuclear ribonucleoprotein C like 1)
Description:
May play a role in nucleosome assembly by neutralizing basic proteins such as A and B core hnRNPs.
Synonyms: HNRPCL1
Tractability: PROTAC: ubiquitination databases record sites on it.
Gene: Protein-coding gene on chromosome 1 (12,847,377 to 12,848,720, reverse strand). Ensembl gene ENSG00000179172.
Subcellular location: Nucleus
Subcellular location (Human Protein Atlas): Nucleoplasm
Gene Ontology:
Molecular function: identical protein binding; protein binding; RNA binding; nucleic acid binding
Cellular component: nucleus
Genetic constraint (gnomAD): Loss-of-function variants: 15 observed, 19.25 expected, observed/expected ratio (o/e) 0.78, 90% interval 0.52 to 1.2. The upper end of that interval is the gene's LOEUF score, 1.2, which puts it in group 5 of 6, group 1 being the genes least tolerant of losing a copy. Missense variants: 327 observed, 344.01 expected, observed/expected ratio (o/e) 0.95, 90% interval 0.87 to 1.04. Synonymous variants: 110 observed, 127.24 expected, observed/expected ratio (o/e) 0.86, 90% interval 0.74 to 1.01.
Homologues: Orthologues: rabbit HNRNPC (90% identical), mouse Hnrnpc (89% identical), rat LOC100911576 (89% identical), tropical clawed frog hnrnpc (76% identical). Paralogues in human: HNRNPCL2 (96% identical), HNRNPCL3 (94% identical), HNRNPCL4 (94% identical), HNRNPC (91% identical), RALYL (45% identical), RALY (43% identical).
Diseases named in the same sentence as HNRNPCL1 in open-access papers:
HNRNPCL1 is named in the same sentence as 4 diseases in open-access papers, as found by Europe PMC text mining. Sharing a sentence is not in itself a finding about the gene and the disease. The quoted sentences say what the papers report.
lymph node metastases (1 paper, 2024). "Moreover, HC-SMGs such as MUC19, MAN2A1 and HNRNPCL1 were exclusively mutated in rNEN-L patients with lymph node metastases, suggesting their involvement in the increasingly aggressive behavior of this disease." (PMID 39548061, 2024).
pancreatic cancer (1 paper, 2021). "For instance, compared to the second sample, HNRNPCL1 in the first sample indicates an increased probability of suffering from pancreatic cancer." (PMID 34150649, 2021).
cancer (2 papers, 2023). A tumor composed of atypical neoplastic, often pleomorphic cells that invade other tissues. "In addition, the pharmacogenomic study of the DEPs in GSCA also showed that the downregulation of proteins such as PRDX4, GDI1, and YWHAE and the upregulation of proteins such as CLEC3B, KRT38, KRT37, and HNRNPCL1 were linked to higher sensitivity toward 30 pan-cancer CTRP drugs." (PMID 37900279, 2023). "We also included four additional splicing regulatory genes (HNRNPA2B1, HNRNPH1, HNRNPCL1, and SRPK1) because they are either related to cancer in general or have been associated with telomere biology (HNRNPA2B1:; HNRNPH1:; HNRNPCL1:; SRPK1:)." (PMID 37531400, 2023). "Heterogeneous nuclear ribonucleoprotein C-like 1(HNRNPCL1) upregulated in MCF-7 neutralizes basic proteins, consequently involved in nucleosome assembly and a potential biomarker in cancer." (PMID 37900279, 2023).
tumor (1 paper, 2023). "Four SFs were not significantly different between matched normal and tumor samples (CDC40, HNRNPH1, HNRNPCL1, and HNRNPM)." (PMID 37531400, 2023).